JAK2 (Janus kinase 2)
Diseases named in the same sentence as JAK2 in open-access papers (continued):
Sharing a sentence is not in itself a finding about the gene and the disease.
leukemia (continued). "Combining JAK2 inhibition with chemotherapeutic agents like cytarabine, daunorubicin, or methotrexate may enhance the efficacy of these drugs, making the leukemia cells more vulnerable to treatment." (PMID 40486651, 2025). "Since JAK2 mutations and dysregulated JAK-STAT signaling often contribute to leukemia cell survival, the use of JAK2 inhibitors in combination with conventional chemotherapy can sensitize leukemia cells to chemotherapeutic agents." (PMID 40486651, 2025). "In addition to monotherapy, combination therapies are being investigated to enhance the efficacy of JAK2 inhibitors in pediatric leukemia." (PMID 40486651, 2025). "Leukemia in children is a chronic disease, and long-term therapy with JAK2 inhibitors could have unforeseen consequences, including the potential for secondary malignancies or late-onset toxicities." (PMID 40486651, 2025). "For instance, combining JAK2 inhibitors with HDAC inhibitors like vorinostat or panobinostat may lead to re-expression of tumor suppressor genes and enhance leukemia cell differentiation, thus complementing the effects of JAK2 inhibition." (PMID 40486651, 2025). "Further research proposed that a small molecule target JOSD1 could a promising strategy in JAK2-mutant leukemia patients." (PMID 39143074, 2024). "Targeting JOSD1 using small molecule inhibition could be a novel targeted therapy for leukemias with mutant JAK2." (PMID 39766302, 2024). "Furthermore, the leukemia cells in the subsequent 3 serial recipients generated with Pt 2’s cells were JAK2 WT." (PMID 35259128, 2022). "Pharmacologic suppression of JAK2 could diminish graft-versus-host disease and retain the graft-versus-leukemia effect in allogeneic hematopoietic stem cell transplantation, and was thus suggested to be applied in diseases including organ transplant rejection." (PMID 35710633, 2022). "The first association between JAK2 mutations and abnormal myelopoiesis was obtained from fly studies, where acquired mutations in the Drosophila melanogaster JAK counterpart Hopscotch (Hop) gave rise to a leukemia-like condition." (PMID 33672930, 2021). "Since in vitro differentiation of hiPSCs toward B-lymphoid cells remains a challenging task, we aimed to investigate a JAK2 fusion, which occurs in leukemia of the myeloid and lymphoid lineages, and whose expression is driven by an N-terminal partner at the onset of hematopoietic development." (PMID 34299194, 2021). "Our results indicated that SOCS5/JAK2/STAT3 was involved in anti-leukemia process of leonurine and that SOCS5 may be a potential diagnostic marker and therapeutic target for CML." (PMID 33935775, 2021). "It is notable that low, rather than high, JAK2 V617F allele burdens at diagnosis have been correlated with shortened leukemia-free survival in PMF." (PMID 34140953, 2021). "Interestingly in the same study, the leukemia burden in both wtRAS(JAK2-mutant) and mutant-RAS xenograft models was reduced via MEK-inhibitor, representing a strongly corroborating evidence to some of the conclusions of our study." (PMID 33247204, 2021). "The fusion protein can be deemed as a truncated form of JAK2 protein with a COOH‐terminal deletion of the pseudokinase and catalytic domains of the JAK2 protein tyrosine kinase, which is unlikely to be the critical pathogenic fusion for leukemia pathogenesis." (PMID 31885183, 2020). "Our research focuses on MPDs (PV, ET) and certain leukemia’s (AML, ALL, CML) for JAK2 V617F mutation, which might constitute a distinctive entity." (PMID 31870101, 2019).
leukemia (continued). "For example, the uncontrolled proliferation of Jak2-V617F positive leukaemia cells might thus be explained by malregulated Gab1 and constitutive activation of Erk1/2 as observed in Jak2-V617F-positve cells." (PMID 31651330, 2019). "For example, cells carrying mutations exclusively in JAK2 specifically upregulated B4GALT1, which is associated with acquisition of drug resistance in leukemia, and cells with mutations in epigenetic modifiers specifically upregulated PITX1, which has been previously implicated in leukemogenesis." (PMID 30765193, 2019). "Four of 10 CRLF2R leukemias, including two that lacked a concomitant JAK2 mutation, markedly induced pSTAT5 in response to short-term TSLP stimulation, while CRLF2NR leukemias did not." (PMID 31318944, 2019). "Based on the in vitro and ex vivo data, we hypothesized that the combinations of a type II JAK2 inhibitor and an mTOR inhibitor would achieve better anti-leukemia control in the in vivo Ph-like B-ALL PDX models." (PMID 29487712, 2018). "In preclinical studies, treatment of JAK2 mutant leukemias with type I JAK2 inhibitors (e.g., Food and Drug Administration [FDA]-approved ruxolitinib) provided limited single-agent responses, possibly due to paradoxical JAK2Y1007/1008 hyperphosphorylation induced by these agents." (PMID 29907650, 2018). "We next sought to determine whether Eμ-Crlf2/Jak2R683G leukemias with sustained knockdown of Jak2 (referred to here as “Jak2 knockdown-persistent cells”) obtained from moribund Dox-treated recipient mice maintained an ability to respond to mutant Jak2." (PMID 29907650, 2018). "However, when Jak2 expression was relieved in these cells, the leukemias were more aggressive, indicating that oncogenic signaling pathways downstream from mutant Jak2 remained intact in these cells." (PMID 29907650, 2018). "Reducing the levels of Mcl-1, irrespective of JAK2 mutation, sensitizes leukemia cells to ABT-263, indicating that Bcl-2 family proteins, such as Bcl-xL and Bcl-2, are necessary to maintain viability when Mcl-1 levels are reduced." (PMID 25781882, 2015). "However, BCR-ABL1-induced myeloid transformation and disease maintenance is independent of JAK2 in mouse models and STAT5 is highly activated despite deletion of JAK2 in these leukemia models." (PMID 25333255, 2014). "Additionally, we investigated how Lgl1 loss modified disease progression in leukaemia models driven by the commonly mutated oncogenes c-Myc and constitutively active JAK2 (in Eμ-Myc and TEL-JAK2 mice respectively)." (PMID 24475281, 2014). "In the current study, we further demonstrate and confirm that the pharmacologic inhibition of JAK1/JAK2 preserves the beneficial anti-leukemia effect previously reported by our group in IFNγR−/− T cells in two different leukemia models (A20 lymphoid leukemia and APL myeloid leukemia)." (PMID 25289677, 2014). "Taken together with other reports, our findings suggest that STAT5 signalling may be a general feature of JAK2-translocation leukemia/lymphoma and link clinical aspects of cutaneous lymphoma with physiological T-cell differentiation." (PMID 23372669, 2013). "Fusions of the tyrosine kinase domain of JAK2 with multiple partners occur in leukemia/lymphoma where they reportedly promote JAK2-oligomerization and autonomous signalling, Affected entities are promising candidates for therapy with JAK2 signalling inhibitors." (PMID 23372669, 2013). "Thus, AG-490 suppresses several signaling pathways, including IL-2-mediated signaling, which is upstream of JAK3 and STAT5A and B. Generally, AG-490 can be used to control the abnormal constitutive activation of JAK2 in leukemia cell lines." (PMID 24170986, 2013). "Besides JAK2, STAT5 can be persistently activated in leukemias by the BCR/ABL tyrosine kinase and mutations in c-KIT or FLT-3." (PMID 23565285, 2013).
leukemia (continued). "Together these findings suggest that adult and pediatric patients with BCR-ABL-negative leukemia and JAK2 overexpression may benefit from targeted therapies." (PMID 22384256, 2012). "This heterogeneity complicates the development of universal therapies, as JAK2 mutations or JAK-STAT pathway dysregulation may not be present or play a prominent role in all cases of leukemia." (PMID 40486651, 2025). "Furthermore, it has been shown that when cells have a significantly high JAK2 V617F allele burden, patients may develop PMF, which may then progress to leukemia, along with the presence of constitutive symptoms." (PMID 40429745, 2025). "Other mutations in JAK2 or STAT proteins may also lead to similar outcomes, including increased sensitivity to cytokines and dysregulated immune responses, which contribute to the malignant phenotype in pediatric leukemia." (PMID 40486651, 2025). "Moreover, through a compound screen, followed by chemical proteomics and compound optimization, WWQ-03-012 is discovered, which selectively degrades mutant JAK2, induces primary leukemia cells death, and inhibits MPN progression through targeting DESI2 enzymatic activity in vitro and in vivo." (PMID 41332324, 2025). "Additionally, JAK2 inhibition may promote the differentiation of MDSCs and Tregs, which are known to contribute to immune suppression in leukemia, thereby improving the overall immune response." (PMID 40486651, 2025). "Furthermore, combination therapies that combine JAK2 inhibitors with chemotherapy, immunotherapy, or epigenetic modulators may enhance the therapeutic effects by targeting multiple mechanisms of leukemia pathogenesis simultaneously." (PMID 40486651, 2025). "While these data show there are multiple routes to transformation of post-MPN sAML, the single cell genomics clearly show that the leukemia-initiating mutations are not always present within the JAK2-mutant clones and can arise independently and outcompete the MPN cells to drive transformation." (PMID 41333431, 2025). "In the prophylactic setting, pairing JAK2 inhibition with established strategies like post-transplant cyclophosphamide (PTCy) or abatacept may enable steroid-sparing regimens that maintain graft-versus-leukemia (GvL) activity." (PMID 40722603, 2025). "For instance, in one patient, a second episode of acute lymphoblastic leukemia (ALL) from 13 years after the original occurrence was determined to be a very late relapse rather than a new leukemia on the basis of a shared JAK2 driver variant and was therefore treated with relapse therapy." (PMID 36585449, 2023). "JAK2‐V617F leukemia cell lines could be re‐sensitized to ruxolitinib after a period of withdrawal." (PMID 37206258, 2023). "In addition, HR and/or c-NHEJ deficiency could be induced by the treatment of leukemia/solid tumors with the tyrosine kinase inhibitors (TKi) against the cancer-driven oncogenic tyrosine kinases (e.g., FLT3(ITD), JAK2(V617F), c-KIT(N822K), IGF-1R, EGFR)." (PMID 36497275, 2022). "Similarly, in the basic study of JAK2-V617F-positive leukemia cells, ruxolitinib may inhibit cell proliferation through dephosphorylation of the JAK2 substrate STAT5 and further regulation of the mTORC1/S6K/4EBP1 signal pathway." (PMID 34016786, 2021). "In addition to leukemia-driving mutations, we have identified recurrent pathogenic mutations CRLF2 p.F232C (n = 7), TYK2 p.A413T (n = 7), JAK2 p.R683G (n = 4), KRAS p.G12D (n = 4), FLT3 p.Y842C (n = 3) and PTPN11 p.D61V (n = 3), previously frequently found in pediatric ALL." (PMID 34830809, 2021). "This was concluded after realizing that often in human leukemia there is oligomerization of JAK2 molecules which renders them constitutively active; this aggregation is due to the occurrence of a genetic fusion between the JAK2 catalytic domain and the oncogenic transcription factor TEL." (PMID 33312162, 2020).
leukemia (continued). "Moreover, we demonstrated that while mutant Jak2 can cooperate with Crlf2 to drive development of leukemia in mice, genetic depletion or pharmacological inhibition of Jak2 served merely to delay proliferation of the leukemias, resulting in a modest therapeutic response in vivo." (PMID 29907650, 2018). "However, consistent with the apparent global up-regulation of Myc target genes in chronic Jak2 knockdown Eμ-Crlf2/Jak2R683G cells, c-Myc protein levels were prominently up-regulated in Eμ-Crlf2/Jak2R683G leukemia cells following sustained Jak2 depletion (shJak2.3323, C#8 M7 and M8)." (PMID 29907650, 2018). "Additionally, loss of Lgl1 does not alter leukaemia driven by constitutive Notch, c-Myc or Jak2 signalling." (PMID 24475281, 2014). "In particular, an activating point mutation in JAK2 (JAK2V617F) has been described with high frequency in chronic myeloproliferative disorders (MPD) and constitutive JAK2 activation caused by chromosomal translocations has been reported in various types of leukemia." (PMID 21533169, 2011). "At leukemia, high DUSP6 can activating Janus kinase 2 (JAK2) signaling pathway to promote tumor progression." (PMID 40936711, 2025). "The JAK2 gene, involved in the JAK-STAT signaling pathway, has emerged as a central player in the pathogenesis of various hematologic malignancies, including leukemia." (PMID 40486651, 2025). "The JAK2-STAT signaling pathway plays a critical role in the survival, proliferation, and differentiation of hematopoietic cells, including leukemia cells and its dysregulation is frequently observed in various types of leukemia." (PMID 40486651, 2025). "Future research should focus on combining JAK2 inhibitors with other targeted therapies, such as inhibitors of the PI3K/AKT or MAPK pathways, which are frequently activated in leukemia." (PMID 40486651, 2025). "These inhibitors block the kinase activity of JAK2, thereby preventing the phosphorylation and activation of STAT proteins and the downstream signaling that drives leukemia progression." (PMID 40486651, 2025). "Dysregulated JAK2-STAT signaling can impair immune surveillance, allowing leukemia cells to evade detection and destruction by the immune system." (PMID 40486651, 2025). "Additionally, dual inhibitors that target both JAK2 and other signaling molecules implicated in leukemia, such as FLT3, BCR-ABL, or RAS, may provide a more comprehensive therapeutic approach for patients with relapsed or refractory leukemia." (PMID 40486651, 2025). "JAK2 dysregulation in the TME contributes to immune suppression, fostering an environment in which leukemia cells are protected from the immune system." (PMID 40486651, 2025). "We validated our microarray analysis by confirming the mRNA downregulation of two genes related to leukemia (EZH2 and JAK2), as well as the expression levels of 5 randomly selected proteins." (PMID 37801090, 2023). "To further study the correlation between JAK2 signaling and RAB27B expression, we compared multiple leukemia cell lines and found that they exhibit a wide range of RAB27B and RAB27A expression levels." (PMID 37317963, 2023). "Pro- and anti-apoptotic proteins were reported as the targets of JAK2/STAT signaling in various tumors, such as leukemia and lymphoma." (PMID 36355485, 2022). "TQ noticeably reduces the phosphorylation of EGFR at tyrosine-1173 residues and JAK2 in vitro in HCT 116 human colon cancer cells and downregulates the Jak2/STAT3 signaling pathway in human melanoma cells and HL60 leukemia cells." (PMID 35956766, 2022). "Hyperactivation of JAK2/STAT3 signaling transduces oncogenic signals to promote CML cells growth, leukemia stem cells survival and therapeutic resistance, thus disease evolution." (PMID 33935775, 2021).
leukemia (continued). "Different types of leukemia harbor genomic aberrations in all four JAKs (JAK1, JAK2, JAK3, and TYK2), most of which are activating somatic mutations and less frequently translocations resulting in constitutively active JAK fusion proteins." (PMID 33672930, 2021). "WP1066 is an analog of a less potent Jak2 inhibitor, AG490, which has been previously shown to inhibit the growth of various cancer cells, such as renal cell carcinoma and leukemia." (PMID 34680353, 2021). "In pediatric ALL, downregulation of SOCS3 mRNA expression led to persistent activation of JAK2/STAT3 and concomitant activation of anti-apoptotic response and leukemia progression." (PMID 34439155, 2021). "BCR-ABL1 and JAK2 proteins regulate STAT5 phosphorylation and these proteins are drug targets for therapeutic intervention in leukemia." (PMID 30687103, 2018). "Treatment of these leukemias with CHZ868 resulted in apoptosis; however, we demonstrate that this compound remained potent even in JAK2-depleted CRLF2/JAK2 mutant B-ALLs, indicating a putative off-target effector mechanism." (PMID 29907650, 2018). "Nevertheless, the mice results provided the proof of principle of using both JAK2 and HSP90 inhibitors to treat the IM-resistant BCR-ABL positive leukemia." (PMID 27551334, 2016). "Here we report establishment of a new leukemia cell line, PVTL-1, homozygous for JAK2-V617F from a 73-year-old female patient with acute myeloid leukemia (AML) transformed from MPN." (PMID 24404189, 2014). "We believe that abnormal fusion transcripts involving JAK2 should be investigated in patients with atypical CML and acute types of leukemia." (PMID 22384256, 2012). "Innovative approaches, such as the development of allosteric inhibitors or dual inhibitors targeting multiple pathways (e.g., JAK2 and FLT3), may offer more effective treatments for leukemia subtypes that are refractory to current therapies." (PMID 40486651, 2025). "Pharmacologic inhibition of JAK2 has been shown to suppress STAT1/STAT3-driven cytokine responses, reduce Th1/Th17 polarization, and preserve Treg stability, while maintaining graft-versus-leukemia (GvL) effects in preclinical models." (PMID 40722603, 2025). "Independent of such details, our data and unbiased, large-scale analyses demonstrate that leukemia cells with wild-type JAK2 are not compromised in growth when JAK2 is depleted." (PMID 40877230, 2025). "By targeting the residual leukemia cells that survive chemotherapy and HSCT, JAK2 inhibitors may improve the outcomes of transplantation and reduce the likelihood of relapse." (PMID 40486651, 2025). "Analyses in the DepMap database illustrate that the elimination of JAK2 does not significantly compromise the proliferation of leukemia cells harboring wild-type JAK2." (PMID 40877230, 2025). "FLT3 inhibitors such as midostaurin and gilteritinib target FLT3 mutations seen in AML, while JAK2 inhibitors such as ruxolitinib inhibit JAK2, which may be activated in KMT2A‐r leukemia." (PMID 39428967, 2024). "A previous study showed that Leonurine plays an anti-leukemia role by inhibiting the proliferation, migration and colony formation of chronic myeloid leukemia cells and promoting their apoptosis through the miR-18a-5p/SOCS5/JAK2/STAT3 axis." (PMID 38267898, 2024). "We see important biological differences in the ability of phosphorylatable vs. non-phosphorylatable CARM1 to support leukemia cell proliferation and demonstrate the therapeutic relevance of targeting both JAK2-V617F and CARM1 in JAK2-V617F-positive cells." (PMID 38649367, 2024). "The inhibition of Janus Kinase 2 (JAK2) either by small-molecule inhibitor AG490 or by knockdown with shRNA results in an increase in β-TrCP and GSK3α/β at both the mRNA and protein level in both human leukemia Jurkat cells and human erythroleukemia HEL cells." (PMID 37686524, 2023).